CD24 (CD24 molecule)
Diseases named in the same sentence as CD24 in open-access papers (continued):
Sharing a sentence is not in itself a finding about the gene and the disease.
breast tumors (continued). "Chang and his colleagues have showed that increased EZH2 expression in CD44+ /CD24-/low breast tumor initiating cells correlated with the increased percentage of this specific subpopulation." (PMID 24345883, 2013). "On the other hand, claudin-3, a tight junction protein depleted in CD44+/CD24- CSC enriched basal/mesenchymal breast tumors, was among the most down regulated genes in SK-β1-C1." (PMID 23991019, 2013). "MCF7-HER2 cell lines as well as HER2 positive breast tumor tissues showed the high CD24 positive cell population." (PMID 24386318, 2013). "We observed variations in the prevalence of CD44+/CD24- tumor cells in breast tumors of different subtypes." (PMID 22762532, 2012). "Breast tumors expressing CD44+CD24-/low immunophenotype showed relationship with HIF-1α (p = 0.039) and negativity for HER-2 (p = 0.013)." (PMID 21824412, 2011). "The relationship between hypoxia markers and CD44+CD24-/low immunophenotype in breast tumors still poorly understood." (PMID 21824412, 2011). "Double-staining immunohistochemistry was used to quantify CD44 and CD24 expression in 240 human breast tumors for which information on other tumor markers and clinical characteristics was available." (PMID 18559090, 2008). "Our results demonstrate a clear variation in the prevalence of CD44+/CD24- tumor cells between breast tumors of different subtypes." (PMID 18559090, 2008). "Cells from primary human breast tumors with a CD44+/CD24-/low phenotype enrich for tumor formation in vivo." (PMID 18366788, 2008). "MK-0752 is a gamma-secretase inhibitor, already with a phase II clinical trial completed, that showed promising results targeting BCSCs, since a decrease in CD44+CD24- population, as well as decreased mammosphere forming efficiency, was observed in samples from breast tumour serial biopsies." (PMID 35326385, 2022). "The CD44+/CD24 low/− population has been isolated from the primary breast tumors." (PMID 36585652, 2022). "According to that, each given breast tumor cell may convert into CD24+ phenotype made possible by the presence of an intracellular pool of CD24." (PMID 34426608, 2021). "Nuclear CD24 was described in breast tumor biopsies and the existence of nuclear CD24 species could explain the aggressiveness of bladder cancer cells, negative for surface CD24." (PMID 34360932, 2021). "Moreover, tumors or cell lines with low levels of SPN showed an enrichment of CD44+ CD24- cells 17, which have been proposed to be cancer-initiating cells in breast tumors 20,21." (PMID 33537097, 2021). "Specifically, the mammary gland tissues and spontaneous tumors were harvested from mice 6 h after HS201 (100 nmol/mouse) injection, enzymatically digested into single breast tumor cells or mammary epithelial cells, stained with CD24 and CD45, and analyzed by an LSRII flow cytometer." (PMID 32385408, 2020). "This was further confirmed by immunofluorescence, where spheroids were labelled with CD44+/CD24−/low/ABCG2/KI67 for CSCs derived from breast tumors, and CD133+/CD44+/ABCG2/Ki67 for prostate and ovarian tumors; except for the prostate LnCap CSCs, which were not CD44+." (PMID 28536422, 2017). "Our results indicate that CD24 expression in breast tumors may indicate sensitivity to anti-IGF1R therapy." (PMID 27179633, 2016). "In MMTV-PyMT and Apc1572T/+ breast tumors, CD24 was strongly but heterogeneously expressed during early tumorigenesis, but decreased in more advanced stages, and accordingly was increased in poorly differentiated lesions compared with well differentiated lesions." (PMID 26978528, 2016). "Here, CD24+CD90+ cancer cells from primary breast tumors of MMTV-PyMT mice were obtained by FACS." (PMID 27542270, 2016).
breast tumors (continued). "For this purpose, we purified bCSCs flow-cytometrically from primary breast tumors on the basis of the cell surface phenotype CD44+/CD24-/low and confirmed their stemness properties on the basis of the expression levels of the following markers: MRP1 and ABCG2, ALDH1, and Oct-4, Sox-2, and Nanog." (PMID 25315241, 2014). "Indeed, VEGF C expression was found to correlate with the CD44+/CD24-low + mammosphere (MS) signature (Pearson's r = 0.61) and, importantly, also with gene sets that are upregulated in breast tumors after chemotherapy (Pearson's r = 0.51)." (PMID 25358638, 2014). "Recent studies have identified that TNBC breast tumors may also have a higher content of CD44+/CD24- cells." (PMID 24167614, 2013). "Here we demonstrated that CD44+CD24-/low breast tumors show an association with HIF-1α status, but not with CAIX." (PMID 21824412, 2011). "There are evidence that hypoxia could drive the maintenance of CSC, via HIF-1α expression, but it still to be determined whether hypoxia markers are expressed in breast tumors presenting CD44+CD24-/low immunophenotype." (PMID 21824412, 2011). "Several groups identified a small subpopulation of highly tumorigenic cells from human breast tumors bearing the CD44+CD24-/low lineage phenotype, which have drug-resistant phenotype and the capacity to form tumors after transplantation in nonobese diabetic/severe combined immunodeficient mice." (PMID 18241344, 2008). "Interestingly, we found three reports that define CD24 as a luminal-like protein in breast tumor cell lines, as a marker whose expression is close to the basal-like gene cluster or whose expression falls into the ER/PR-negative cluster, in breast tumors." (PMID 17474988, 2007). "Thus, the resistance of HER2-high breast tumors to trastuzumab may be due to an increased population of HER2-low CD44+/CD24 mesenchymal cells at the late passages." (PMID 34575017, 2021). "Moreover, metastasis has been suggested to be an early event during breast tumor development, and dissemination might therefore already take place when CD24 levels are still high." (PMID 26978528, 2016). "Breast CSCs (BCSCs) represent a small subset of cells that contain stem cells in breast tumors, characterized by the CD44+/CD24 expression profile." (PMID 38255288, 2024). "Whereas CD24–/loCD44+ cells have been shown to initiate breast tumors in NOD/SCID mice, high CD24 expression increases metastasis, and CD24+CD90+ cells initiate metastases that display a mesenchymal phenotype." (PMID 39225101, 2024). "The 3rd generation 3D breast tumor spheroids displayed a stemness phenotype, as assessed by the methylcellulose clonogenic assay, riboflavin uptake, HIF-2α and CD47, CD44, CD24, and CD133 CSC marker expression." (PMID 34205080, 2021). "This study also examined the expression of CSCs markers (CD44 and CD24) and EMT markers (E-cadherin, β-catenin, vimentin, and N-cadherin) in the isolated breast tumor cells and in tumor tissues by qRT-PCR." (PMID 33282946, 2020). "Recent data have shown that the JAK2/STAT3 pathway is preferentially activated in CD44 + CD24- breast CSCs through the excessive production of IL6 and promotes CSC growth in breast tumors." (PMID 31511084, 2019). "Other researchers also showed that breast tumors express CD44 and CD24 but are very heterogeneous among different tumors and also within the tumor." (PMID 26968831, 2016). "Subsequently, we investigated the distribution of CD19+CD24+CD38+ Bregs and various subsets in the PBMCs of breast tumor patients." (PMID 27762298, 2016).
breast tumors (continued). "Here, various markers have been utilized in the detection of CSC population within breast tumor cells, such as sphere forming assay, CD44 and CD24 cell surface markers, PKH fluorescent dye, and expression of pluripotency markers." (PMID 25380486, 2014). "In breast tumors, a CD44+CD24–/lowESA+ lineage subpopulation was originally identified as the tumorigenic (tumor-initiating) fraction." (PMID 22901246, 2012). "In human breast tumors, the CD44+/CD24-/low phenotype has been reported to have stem cell properties." (PMID 20696077, 2010). "Most current studies have emphasized the identification of cancer stem cell subpopulations from breast tumors using CD44 and CD24." (PMID 20027313, 2009). "Interestingly, YAP/TAZ and SOX2 were found to be significantly upregulated in the CD44+/CD24− and ALDH+ population isolated from patient breast tumors, adherent cells and mammospheres." (PMID 39979255, 2025). "In addition, the percentage of CD44high/CD24-/low cells, which have been shown to be enriched in CSCs of some TNBC lines and human breast tumours, was decreased in TCOF1-depleted HCC1806 cells." (PMID 34718356, 2022). "The results showed that there was no significant change in CD24 mRNA expression in breast tumor cells (T = −1.116, P = 0.278)." (PMID 33282946, 2020). "Interestingly, within the breast tumor heterogeneity, distinct bCSC types are found: CD24−/CD44+; ALDH+; and CD24−/CD44+/ALDH+, all with different features and transcriptomic profiles." (PMID 29734696, 2018). "A high expression of CD44 paired with absent/low expression of CD24 on the cell surface has been used as a CSC marker in breast tumours." (PMID 28863191, 2017). "In this study, we focused on the intratumor morphological heterogeneity in IC NST, performed 3D imaging, whole genome copy-number and transcriptome profiling of the different morphological structures of breast tumors and analyzed the distribution of CD44+CD24- CSCs." (PMID 28977854, 2017). "Even within breast tumors, the accepted combination of surface markers CD44/CD24 shows differences among different subtypes, being the CD44+/CD24− phenotype common in the basal subtype, specially in BRCA1 hereditary tumors, but surprisingly scarce in HER2-positive tumors." (PMID 25414831, 2014). "Given that many functional properties of normal stem cells are shared by TICs, we isolated and examined subpopulations from the breast tumors, based on expression of cell-surface markers CD29 and CD24, which were used to enrich for mouse normal mammary stem cells." (PMID 23300950, 2013). "Subsequently, CD24 and CD44 were selected as CSC markers in breast tumors." (PMID 22359637, 2012). "Similar to the results of Honeth and co-workers, we found 35% of cases showing CD44+CD24-/low immunophenotype, suggesting that not all breast tumors contain cells with this phenotype, as described by Al-Hajj in 2003." (PMID 21824412, 2011). "Recent studies reported that breast tumors may contain only CD44+, or only CD24+ cells, as well as mixed cell populations, and that CD44+ tumor cells express many stem-cell markers." (PMID 20585577, 2010). "A recent study demonstrated CD44+/CD24- cells in 59% of human breast tumors, further supporting that not all breast tumors contain cells with this phenotype." (PMID 18559090, 2008). "However, CD24 positivity or negativity rather than expression intensity correlated with poor survival in human prostate and breast tumor patients." (PMID 26978528, 2016). "The increase in the expression of CD44 and CD24 in the explant cultures that were generated from a broad range of breast tumour types, and not just the basal type, indicated a chemotherapy-induced expression of CD44Hi and CD24Hi cells rather than an enriching of the CSCs." (PMID 25669750, 2015).
breast tumors (continued). "Moreover, they also report that in MCF12A mammary epithelial immortalized cells, the CD44+/CD24-/low profile, found to enrich for cancer stem cells in primary breast tumors, failed to enrich for mammosphere initiating cells." (PMID 24124614, 2013). "The prevalence of CD44+/CD24-/low cells within breast tumors, however, has not been significantly associated with clinical characteristics – although tumors with a higher fraction of CD44+/CD24- cells were more commonly found in patients diagnosed with distant metastases." (PMID 18559090, 2008). "CSCs from breast tumors are suggested to have high expression of CD44 and low or no expression of CD24." (PMID 35012489, 2022). "In breast tumors, the cancer stem cells (CSC) can be identified by the expression ofCD44 and by low or absent expression of CD24 (CD44+/CD24-/low)." (PMID 31384244, 2019). "In the non-breast tumor cells, HT29 and HeLa, no change of expression was observed with both cells displaying a typical CD44+/CD24- epithelial phenotype." (PMID 26185996, 2015). "When human breast tumors were propagated in non-obese diabetic severe combined immunodeficiency (NOD/SCID) mice, it was observed that as few as 100 of the CD44+CD24−/low cells were able to give rise to new tumors." (PMID 25905435, 2015).
colorectal cancer (69 papers, 2012 to 2025). A primary or metastatic malignant neoplasm that affects the colon or rectum. "In our investigation of senescence-associated signatures in colorectal cancer, CD24 emerged as the most critically prioritized gene, exhibiting the highest importance score." (PMID 40777020, 2025). "We aimed to investigate the underlying mechanism and role of CD24 on colorectal cancer (CRC) angiogenesis." (PMID 27494878, 2016). "In contrast to the results reported here, CD24 deficiency resulted in resistance to chemically induced colorectal cancer, and tumor formation in ApcMin mice that spontaneously develop intestinal tumors was almost completely prevented on a CD24-/- background." (PMID 26978528, 2016). "In non-hematopoietic cells, a large body of literatures has implicated CD24 expression in tumorigenesis and progression in a wide range of epithelial cancers including pancreatic, prostate, ovarian, breast and colorectal cancers." (PMID 27659530, 2016). "High CD24 expression is associated with promoting proliferation in lung, prostate, and colorectal cancer, while low CD24 expression is associated with proliferation in BCSCs." (PMID 26301220, 2015). "For instance, in colorectal cancer, some studies have indicated that high levels of CD24 significantly shorten patient survival time, whereas another study showed that high levels of CD24 were associated with prolonged patient survival." (PMID 39791710, 2024). "If confirmed in prospective studies, CD24 and other immune related polymorphisms may guide the use of cetuximab in patients with advanced colorectal cancer." (PMID 33065994, 2020). "CD24 expression is associated with human colorectal cancer (CRC)." (PMID 22731636, 2012). "In the same study the percentage of CD24 high CD38 high (transitional) B cells was lower in tumor samples than in peripheral blood of colorectal cancer patients and transitional B cells were very rare in early-stage CRC (p < 0.05)." (PMID 41008839, 2025). "Critically, targeting the CD24-Hsp90 interaction emerges as a potential therapeutic approach for colorectal cancers." (PMID 39936995, 2025). "Research has indicated that musarin significantly inhibits the proliferation of different colorectal cancer cells in a dose-dependent manner, and it particularly inhibits the proliferation of CD24+ CD44+ HT29 cells with CSC characteristics." (PMID 40507156, 2025). "The short mucin-like cell surface protein CD24 has been reported to promote colorectal cancer by driving pro-angiogenic signals." (PMID 39936995, 2025). "Specifically, in colorectal cancers, CD24 upregulation reportedly occurs at an early stage during colorectal cancer progression." (PMID 37894750, 2023). "We reviewed them and selected CD24, an immune target, for meta-analysis with colorectal cancer (CRC) to investigate the correlation between CD24 expression and CRC." (PMID 35938128, 2022). "HSP90 is needed to cooperate with CD24 to enhance STAT3‐mediated VEGF transcription to inducing colorectal cancer angiogenesis." (PMID 35928554, 2022). "A meta-analysis of the correlation between CD24 expression and clinicopathological features and prognosis in colorectal cancer was conducted." (PMID 35938128, 2022). "Suppression of GRP78 downregulated CD24 expression in colorectal cancer and increased sensitivity to the chemotherapy agent oxaliplatin." (PMID 35740372, 2022). "A recent study reported that SOX2 expression primarily coincided with CD44+ and ALDH1+ population in pancreatic CSCs and CD44+ and CD24+ in colorectal cancer." (PMID 33445526, 2021). "Our previous studies have shown that CD24 levels were elevated in transformed enterocytes compared to normal cells, and that CD24 is overexpressed in colonic mucosa already at an early stage of colorectal cancer carcinogenesis." (PMID 34575716, 2021).